ZPR1P1 (ZPR1 pseudogene 1)
Synonyms: 354J5; formerly ZNF259P; ZNF259P1
Gene: Transcribed processed pseudogene on chromosome 6 (108,785,689 to 108,787,053, reverse strand). Ensembl gene ENSG00000219565.
Diseases named in the same sentence as ZPR1P1 in open-access papers:
ZPR1P1 is named in the same sentence as 2 diseases in open-access papers, as found by Europe PMC text mining. Sharing a sentence is not in itself a finding about the gene and the disease.
ZPR1P1 shares sentences with these, for which no sentence is quoted: lung adenocarcinoma (1 paper); tumor (1).